FLNA (filamin A)
Diseases named in the same sentence as FLNA in open-access papers (continued):
Sharing a sentence is not in itself a finding about the gene and the disease.
melanoma (continued). "In a panel of human melanoma cell lines established from cancer patients, a correlation between filamin-A expression and drug sensitivity was observed, i.e. the lower filamin-A level the cell line had, the more sensitive the cell was to bleomycin and cisplatin treatment." (PMID 23388158, 2013). "Our findings that concomitant expression of active oncogenic R-Ras and full-length wild type FLNa induced melanoma cell migration suggest that FLNa may relay R-Ras signals to integrins to regulate migration and subsequently contribute to tumor metastasis." (PMID 20585650, 2010). "Immunostaining for the presence of a fibronectin matrix demonstrated that an increase in matrix formation occurred in the melanoma cultures expressing both activated R-Ras and FLNa in comparison to cells expressing R-Ras and FLNaΔ3 (repeat 3 deleted) or R-Ras alone." (PMID 20585650, 2010). "Driving the receptor to the plasma membrane and/or stabilizing it would seem a likely possibility, but our results have been quite conclusive showing the presence of receptor in the plasma membrane of M2 melanoma FLNa-deficient cells and in HEK293 cells depleted of FLNa." (PMID 20808917, 2010). "Therefore, we speculated that TRIP13 exerted the role of the PI3K/AKT pathway activation and EMT of melanoma cells through interaction with FLNA." (PMID 36268276, 2022). "Thus in melanoma cells R-Ras and FLNa may cooperatively promote metastasis by enhancing cell migration." (PMID 20585650, 2010). "Furthermore, in our transient transfection experiments, where the expression levels of FLNa were similar, we observed a significant increase in melanoma cell migration upon co-expression of active R-Ras suggesting that R-Ras and FLNa work in tandem to support migration." (PMID 20585650, 2010). "In conclusion, the results of this study demonstrate the important role of TRIP13 in promoting melanoma progression and EMT via the FLNA/PI3K/AKT pathway." (PMID 36268276, 2022). "To confirm the interaction between TRIP13 and FLNA, we performed immunofluorescence assays and confirmed that TRIP13 and FLNA colocalized in melanoma cells." (PMID 36268276, 2022). "Human melanoma cell lines lacking filamin A expression are known to be non-motile and display significant membrane blebbing." (PMID 38958472, 2024). "Filamin A is also necessary for the normal function of BKCa channels, which normally traffic to the plasma membrane in A7 melanoma cells with filamin A but have trouble trafficking in M2 cells without filamin A." (PMID 35162934, 2022). "In the present study, we found that TRIP13 also activates AKT signaling to promote melanoma malignant phenotypes which is consistent with the previous research; we further discovered that TRIP13 activates AKT signaling by directly interacting with FLNA." (PMID 36268276, 2022). "Since CFTR clusters form spontaneously in HBE cells we used M2 and A7 cells (neural crest-derived melanoma cell lines without and with filamin A, respectively) to examine the effects of detergent on clustering." (PMID 35060604, 2022). "For example, in melanoma cells, ROR2-FLNA interaction is critical for WNT5A-induced JNK phosphorylation, cytoskeleton remodeling, and cell migration, and WNT5A-ROR2 binding induces calpain expression and its cleavage of FLNA leading to increased invasiveness." (PMID 33134326, 2020). "Somehow in analogy, FLNA is not expressed in all melanomas indicating that it is not an absolute requirement for the development of these tumors, but its co-expression with Pro-PrP significantly enhance the capacity of melanoma cells to migrate." (PMID 31752162, 2019). "Filamin A (FLNA), a scaffolding protein involved in intracellular trafficking of several transmembrane proteins, has been shown to interact with the SST2 in melanoma and pancreatic cell lines." (PMID 30232095, 2018).
melanoma (continued). "Moreover, we have recently demonstrated that activation of NF-κB by extracellular S1P in melanoma cells involved both S1PR1 and S1PR2 and was inversely correlated with the expression of the actin-binding protein FlnA." (PMID 27800303, 2016). "Previous studies looking into FLNa’s role in directed cell migration (chemotaxis) have been carried out primarily in a human melanoma cell line lacking FLNa." (PMID 24205360, 2013). "Previous studies investigating FLNa’s role in cell migration have been primarily carried out in human melanoma cells lacking the FLNa protein." (PMID 24205360, 2013). "Further, by over-expressing PC2N and PC2C in human melanoma A7 cells we found by co-IP that both PC2N and PC2C interact with endogenous FLNA and that the PC2N-FLNA interaction is stronger than the PC2C-FLNA interaction, in agreement with our results obtained from in vitro binding data." (PMID 22802962, 2012). "FLNa is required for melanoma cell migration and melanoma cells that do not express FLNa do not migrate." (PMID 20585650, 2010). "Moreover, in order to investigate the role of FLNA, we used the human melanoma cell models either expressing (A7) or lacking (M2) FLNA." (PMID 35992099, 2022). "In melanoma cells, SST2/SST5 hetero-dimers were also observed, but, interestingly, the absence of FLNA resulted in a significant reduction of their amount under basal conditions, indicating that FLNA is required but not essential for bringing SST2 and SST5 in close proximity to dimerize." (PMID 35992099, 2022).
periventricular nodular heterotopia (44 papers, 2010 to 2025). "Periventricular nodular heterotopia (PVNH) Type 1 is a disease caused by a mutation of the Filamin A (FLNA) gene (MIM # 300049), located on chromosome Xq28." (PMID 41473033, 2025). "Mutations in patients with periventricular nodular heterotopia generally result in FLNA loss of function, with rare surviving males exhibiting partial loss-of-function variants and females carrying more severe mutations." (PMID 40860336, 2025). "FLNA mutations are implicated in several neurodevelopmental disorders, such as periventricular nodular heterotopia (PVNH), leading to neurological symptoms such as epilepsy, intellectual disability and cognitive impairments." (PMID 40365811, 2025). "FLNA gene mutations can cause periventricular nodular heterotopia, which is an X-linked dominant genetic disease in which neurons fail to migrate to the cerebral cortex." (PMID 40735484, 2025). "In patients with combined CIPO, periventricular nodular heterotopia, and cardiovascular changes, mutations affecting both isoforms of FLNA contribute to the complexity of the phenotype." (PMID 40860336, 2025). "The first identified mutation in the FLNA gene was a null one, resulting in periventricular nodular heterotopia (PVNH)." (PMID 37446373, 2023). "Variants in FLNA are associated with periventricular nodular heterotopia, congenital heart disease, thrombocytopenia, among other things, and therefore, she was diagnosed with FLNA deficiency." (PMID 40225162, 2023). "Periventricular nodular heterotopia (PNH) is strongly associated with FLNA mutations, which causes a loss of protein function, meaning developing neuronsfail to differentiate or migrate to the cortex in a timely manner." (PMID 37422633, 2023). "We identified the missense variant p.Arg484Gln on filamin-A (FLNA) in a Turkish family, associated with periventricular nodular heterotopia (PNH)." (PMID 35613087, 2022). "The filamin-A (FLNa) variants reported in the liveborn male patients with periventricular nodular heterotopia." (PMID 35613087, 2022). "We describe here two novel FLNA variants associated with periventricular heterotopia and pulmonary emphysema, with respective alterations observed in platelet function and FLNA expression." (PMID 35156755, 2022). "In this study, the novel p.Arg484Gln (c.1451G>A) variant on filamin-A (FLNA) was identified in a male patient with periventricular nodular heterotopia (PNH) by performing whole exome sequencing analysis." (PMID 35613087, 2022). "Melnick–Needles syndrome and periventricular nodular heterotopia are two usually mutually exclusive phenotypes of F-actin-binding cytoskeletal phosphoprotein Filamin-A mutations." (PMID 34629090, 2021). "The other principal gene implicated in periventricular heterotopia, FLNA, is also implicated in intracellular trafficking, as it has been shown that FLNA facilitates trafficking of β1 integrin to the cell membrane." (PMID 35069108, 2021). "In the patients with Ehlers-Danlos syndrome and periventricular heterotopia, caused by a loss-of-function mutation in the FLNA gene, was detected and found to contribute the development of aortic dilatation in early adulthood." (PMID 34485398, 2021). "FLNA mutations can cause several severe syndromes, including periventricular nodular heterotopias, otopalatodigital syndromes, skeletal dysplasia, lung involvement, and cardiovascular abnormalities." (PMID 34976019, 2021). "Mutations in FLNA (Filamin A), which crosslinks actin filaments and links them to membrane proteins, can be a cause of periventricular heterotopia." (PMID 35069108, 2021). "The role of Filamin A in migration was further supported by the finding that nonsense mutations in the Filamin A gene are associated with the neuronal migration disorder periventricular heterotopia." (PMID 33330471, 2020).
periventricular nodular heterotopia (continued). "The application of WES allowed to identify a heterozygous nonsense variant in the FLNA gene ((NM_001456.3), c.1159C > T p.(Gln387 *)), a gene known for being causative of periventricular nodular heterotopia in an X-linked dominant fashion." (PMID 33105617, 2020). "Mutations in the gene encoding filamin A (FLNA) lead to diseases with high phenotypic diversity including periventricular nodular heterotopia, skeletal dysplasia, otopalatodigital spectrum disorders, cardiovascular abnormalities, and coagulopathy." (PMID 27091362, 2016). "FLNA mutations are associated with classical bilateral periventricular nodular heterotopia and account for the majority of X-linked inherited periventricular heterotopias." (PMID 26541977, 2015). "The most common genetic cause of periventricular heterotopia is the X-linked dominant inheritance of Filamin A (FLNA) gene mutations." (PMID 26541977, 2015). "Periventricular heterotopia (PH) is a human cortical malformation disease associated with mutations in the ArfGEF2 gene and the actin-binding protein Filamin A (FlnA)." (PMID 26733777, 2015). "We present clinical, neuroimaging and mutation data of a large cohort of 47 patients with periventricular nodular heterotopia resulting from heterozygous or rare instances of mosaic FLNA mutations in males." (PMID 26471271, 2015). "A cytoskeleton-associated gene mutations in the filamin A (FLNA) cause periventricular heterotopia (PH), cell cycle prolongation, compromised neural progenitor proliferation, and reduced brain size." (PMID 25522158, 2014). "This patient also had a V528M variant in FLNA that has been reported in a case of bilateral periventricular nodular heterotopia and also as a functional polymorphism." (PMID 24690944, 2014). "Its homologue FLNA (filamin A) is involved in neuronal migration and is implicated in an X-linked dominant form of periventricular heterotopia, a neurological disorder that sometimes involves reading and spelling problems." (PMID 25065397, 2014). "The first two were overlapping duplications in Xq28 in males with CBLH (one of who also had ACC) that included the FLNA gene associated with periventricular nodular heterotopias." (PMID 24098143, 2013). "Familiar periventricular heterotopia with mutation in filamin A (FLNA) gene, an X-linked dominant disorder, can cause West syndrome in males." (PMID 20181122, 2010). "Notably, deleterious mutations in Filamin-A that impair actin binding result in the defective migration of neurons in the cerebral cortex that causes periventricular nodular heterotopia and is linked to neuropsychiatric disease." (PMID 39951537, 2025). "Periventricular nodular heterotopia (PNH) is a cell migration disorder associated with mutations in Filamin-A (FLNA) gene on chromosome X. Majority of the individuals with PNH-associated FLNA mutations are female whereas liveborn males with FLNA mutations are very rare." (PMID 35613087, 2022). "Heterozygous null mutation of FLNA in females causes periventricular nodular heterotopia (PVNH)." (PMID 30813567, 2019). "It is also known that FLNa associates dynamically with Golgi membranes during budding and trafficking of transport vesicles and has been shown that in periventricular nodular heterotopia, a developmental FLNa loss-of-function disease, this vesicle transport is disrupted." (PMID 22870205, 2012). "Interestingly, X-Linked Periventricular Heterotopia is due to mutations in Filamin A and is marked by an aggregation of neurons along the surface of the ventricular zone." (PMID 22384137, 2012). "In contrast to Drosophila, mammals have three filamin proteins, A, B and C. Loss of function mutations in Filamin A are found in the human disease periventricular heterotopia, which is a defect in axonal migration that has been associated with the dynamic regulation of actin." (PMID 21857973, 2011).
periventricular nodular heterotopia (continued). "Notably, mutations of filamin-A, an actin cross-linking protein, cause periventricular heterotopia (PVH) in humans." (PMID 21980468, 2011). "The filamin-A (FLNA) gene, mapped to Xq28, is the most common genetic cause of X-linked bilateral periventricular nodular heterotopia (BPNH), that usually shows anterior predominance." (PMID 38612920, 2024). "Periventricular nodular heterotopia (PNH), associated with FLNA mutations, is a rare clinical condition potentially associated with multiple systemic conditions, including cardiac, pulmonary, skeletal, and cutaneous diseases." (PMID 37422633, 2023). "Mutations and perturbation in the FLNA and FLNB genes are known to cause different developmental disorders in humans, such as bone anomalies, periventricular heterotopia, aortic dissection and aneurysm." (PMID 25419056, 2014). "Patients 301 and 304 were hemizygous and heterozygous respectively for a rare variant in the FLNA, a gene involved in X-linked Periventricular nodular heterotopia, a disease where neurons do not migrate properly during the early development." (PMID 31694657, 2019). "Previous in vitro and in vivo studies showed that in mice, loss of BIG2, a paralog closely related to BIG1, caused periventricular heterotopia (PH) and impairment of neural migration, which is explained by the BIG2-mediated regulation of Filamin A phosphorylation in NPCs." (PMID 28414797, 2017). "Furthermore, unfolding of FLNa23 with consequent weakening of the elasticity of FLNa/F-actin network under high mechanical stress has earlier been connected to FMD and Periventricular Nodular Heterotopia causing mutations." (PMID 28652603, 2017). "The pathogenic variant of FLNA gene mutation in our reported case is not confirmed to have association with periventricular nodular heterotopias (PNH), and our patient was too ill to complete brain MRI." (PMID 27091362, 2016). "The most frequent symmetric manifestation of periventricular nodular heterotopia (PVNH) is located along the walls of both lateral ventricles predominantly in females and results from heterozygous loss of function mutations in the X-linked FLNA gene." (PMID 26471271, 2015). "RNF213 R4810K coexisted with filamin A (FLNA) Gly1623Val fs*41 in a patient exhibiting Ehlers–Danlos-like symptoms and bilateral periventricular nodular heterotopia (PNH), but seizures and MMD-like cerebral vascular formation also appeared." (PMID 40869185, 2025). "In addition, no variants were observed in the known or possible genes for periventricular heterotopia including FLNA, ARFGEF2 and ERMARD, nor were pathogenic variants seen in other known genes implicated for brain malformation syndromes, intellectual disability or ADHD conditions." (PMID 28868155, 2016). "Moreover, pathogenic mutations in several genes have been related to non-syndromic CHD with PDA being a prominent phenotype, including FLNA-related PDA and periventricular heterotopia and MYH11/ACTA2-related PDA and aortic aneurysm." (PMID 36010266, 2022). "In addition to FLNA mutations, duplications and deletions in chromosome 5 which includes Periventricular Nodular Heterotopia 3 (PVNH3) and Periventricular Nodular Heterotopia 5 (PVNH5) have been seen in patients with periventricular heterotopia without mutations in other causative genes." (PMID 26541977, 2015).